CD14 (CD14 molecule)
Diseases named in the same sentence as CD14 in open-access papers (continued):
Sharing a sentence is not in itself a finding about the gene and the disease.
tumor (continued). "We observed that there was upregulation of phosphorylated STAT3 in tumor-treated CD14+/HLA-DRlow/− cells as compared to untreated CD14+ cells by Western blotting." (PMID 24652403, 2014). "In PC patients with primary disease only, the CD14+ cells in the blood have a high HLA-DR expression but these cells only obtain MDSC phenotypic markers when they infiltrate the tumor." (PMID 24652403, 2014). "A significant population of CD14+ cells within the tumor had low HLA-DR expression by flow cytometry, a characteristic of Mo-MDSC." (PMID 24652403, 2014). "Further analysis showed that CD14+ leukocytes correlated with tumor ALDH1 expression (Spearman’s r = 0.2, p = 0.02) and tumors classified as CD14Hi had increased ALDH1Bright cells." (PMID 24652403, 2014). "We observed that patients with predominant CD14+/CD8Low infiltrate in the tumor had a significantly reduced overall survival compared to all other groups (denoted as CD14Low/CD8Low, CD14Hi/CD8Hi, and CD14Low/CD8Hi, p value <0.001)." (PMID 24652403, 2014). "The biological activities of CX3CL1 are mediated by CX3CR1, that is expressed on different cell types such as NK cells, CD14+ monocytes, cytotoxic effector T cells, B cells, neurons, microglia, smooth muscle cells, and tumor cells." (PMID 24799766, 2014). "A cell suspension prepared from solid tumors of the studied mice showed presence of CD4+, CD8+, CD19+, CD94+ as well as CD14+ cell populations in the tumor microenvironment." (PMID 25168124, 2014). "IL-6 can reactivate latent HCMV virus in CD14+ monocytes and dendritic cells, and it is a pro-inflammatory cytokine commonly found in the tumor environment." (PMID 25549333, 2014). "In order to validate this finding, we also cultured human PC tumor cells for sphere formation after they were cocultured with CD14+ cells." (PMID 24652403, 2014). "However, testing a panel of tumor-associated culprits pointed to IL-10 as the most likely candidate, since it was the only tested cytokine that could affect the balance of migrating CD1a+ and CD14+ DDC." (PMID 23875023, 2013). "CD14 moderate cytoplasmic staining was observed in at least 50% of tumor cells and weak staining of 10% of the fibroblasts." (PMID 23497279, 2013). "As the main effector cells of antibody-mediated tumor cell killing of PBMCs are monocytes (CD14+) and NK cells (CD56+), we investigated the singular contributions of these two immune cell populations on ADCC and ADCP activity." (PMID 24330813, 2013). "Proliferation of tumor cells in response to LPS in A549 cells was induced by the ligation of LPS to CD14 and the pattern recognition receptor TLR4 followed by COX-2-dependent PGE2 synthesis." (PMID 22923191, 2013). "Most importantly, combined STAT3 and p38 inhibition supported a shift from CD14+ monocyte-like cells to CD1a+ DC in metastatic melanoma single-cell suspensions, indicating a potential for improved DC differentiation in the tumor microenvironment." (PMID 24324467, 2013). "Flow cytometry analysis of total dispersed tumor cells identified a population of CD14+ myeloid cells, and fractionation using anti-CD14 magnetic beads separated these CD14+ cells from the CD14-negative population with high efficiency." (PMID 23922683, 2013). "CD14+ cells were converted to dendritic cells (DC) and also primed with U251 tumor cell line lysate." (PMID 23758888, 2013). "Normalized distribution (i.e., more mature and less immature DC subsets) was observed for explants taken from patients that had received neoadjuvant chemotherapy: a clear indication that prevailing migration of the immature CD14+ subset was tumor-related." (PMID 24324467, 2013). "In this study, we describe a novel, single-step selection technique that allows purification of freshly harvested stromal cells, as well as isolation of the CD14+ myeloid lineage cells from the excised tumor tissue." (PMID 23922683, 2013).
tumor (continued). "Our results indicate that immunomagnetic isolation of CD14+ monocytes using the CliniMACS® device and their pulsing with whole tumor lysate proteins is a suitable method for clinical-scale generation of high quality, functional DC under GMP-grade conditions." (PMID 23284979, 2012). "In line, our in vitro analyses showed that incubation of PBMCs with tumor cell culture supernatants results in the rapid induction of CD14++CD16+ monocytes." (PMID 22973451, 2012). "DC were derived from CD14+ monocytes in the presence of GM-CSFand IL-4 and during this process we had observed that tumor-derived compoundsimpair differentiation." (PMID 21423807, 2011). "Myelo-monocytic cells expressing the hematopoietic marker CD14 and various vascular markers such as Tie2 (Tie2+ Monocytes), VE-Cadherin, and VEGFR2 have been reported to take part in both ischemia-associated and tumor-associated angiogenesis." (PMID 19545375, 2009). "Once the tumor cell releases these HSPs, the host's antigen presenting dendritic cells, can take up these antigens via the CD14, CD91, TLR2 and 4 receptors." (PMID 19247476, 2009). "The topographical location of the CD14+ cells surrounding the tumor foci and accumulating in tumor blood vessels points to their role limiting tumor growth and expansion." (PMID 14960205, 2004). "Accumulation of CD14+, DR+ cells around tumor foci suggested the extraction of these subsets from the perfusing blood, possibly in response to the local chemotactic signals." (PMID 14960205, 2004). "In the tumor-bearing livers the sinusoidal wash-out contained significantly more of CD14+ and MHC class II cells than that of normal livers." (PMID 14960205, 2004). "Evidently more CD14+ cells accumulating in the tumor vessels than in normal liver sinusoids suggests an additional mechanism of attraction of leukocytes to the growing tumor tissue." (PMID 14960205, 2004). "The second mechanism by which tumours can alter DC maturation affects their differentiation from CD14+ monocyte precursors." (PMID 14562018, 2003). "A number of tumour-derived factors with the capacity of altering the maturation of CD34+or CD14+precursors, including VEGF, TGF-β, IL-10 and PGE2, have been excluded to be implicated in this pathway." (PMID 14562018, 2003). "Moreover, inhibiting CD14 expression in tumor cells reduced the levels of neutrophil-recruiting chemokines by suppressing NFκB signaling, leading to a significant decrease in neutrophil infiltration within the TME." (PMID 41486114, 2026). "To assess whether the in vitro correlation between CD14-expressing tumor cells and NFκB-driven chemokine production translates into the in vivo TME, we conducted RNA-seq analysis comparing MB49-B6 and MBT2-C3H ectopic tumors." (PMID 41486114, 2026). "The results demonstrated high 6PGD expression in tumor-infiltrating CD33+CD14+ M-MDSCs." (PMID 41535266, 2026). "However, Tie2-/CD14+ macrophages and CD68+ tumor-associated macrophages (TAMs) showed uniform stromal distribution." (PMID 42074283, 2026). "We next evaluated whether targeting CD14 in tumor cells could diminish neutrophil recruitment and thereby limit the badscopal effect." (PMID 41486114, 2026). "These reprogrammed cells upregulated activation markers (CD14, CD117) and downregulated suppressive molecules (PD-L1, CD206), driven by a TME rich in GM-CSF, IL-3, and MIP-1α/β, which enabled them to perform bystander killing of antigen-loss tumor variants." (PMID 41301697, 2025). "Moreover, CCR1+CD14+ monocytes present in tumor lesions express PD-L1, B7-H3 and TIM-3, and enhance angiogenesis and metastasis." (PMID 40136652, 2025). "In particular, as M2c macrophages are involved in tumor progression, human CD14+-derived M2 macrophages were employed to assess how the tested formulations could influence these cells’ phenotype." (PMID 40362536, 2025).
tumor (continued). "Additionally, the non-tumor area of the invasive margin-excluded (IME) sample exhibits significant enrichment of CD14+ and CD16+ monocytes, which is consistent with the macrophage definition in the original study." (PMID 39862439, 2025). "In particular, bioinformatics analysis of MC interaction with other cells of the FGF23-producing tumour microenvironment, within an integral range of intertarget distances from 0 to 20 μm, disclosed their most frequent co-localisation with CD14+, CD31+, αSMA+, and CD163+ cells." (PMID 40981193, 2025). "Elevated HLA‐DR expression on CD14+ monocytes remained significantly associated with sNENs after FDR correction, indicating a persistent proinflammatory state that may facilitate tumor proliferation and immune dysregulation." (PMID 41458898, 2025). "These CD14+ cells resemble murine CD11b+ dermal dendritic cells and may contribute to immune modulation depending on the tumor microenvironment." (PMID 40432086, 2025). "Increased CD14‐labeled monocytes in the spleen of tumor‐bearing mice may activate the therapeutic potential of innate immunity through the TLR4 signaling pathway." (PMID 40289661, 2025). "After establishing the tumor cells as distinct from all other cell types present in the tissue, we further characterized both the tumor and lymphocyte populations using a panel of trogocytic markers (CD14, CD16, CD56, and CD45)." (PMID 40440354, 2025). "Additionally, there was an association between the micropapillary growth pattern and decreased CD20−CD79A+ plasma cell and CD14+HLA‐DR− monocytic cell densities within the tumor stroma." (PMID 39917902, 2025). "Additionally, scRNA-seq confirmed that elevated sphingolipid metabolism levels occur in CD14+ monocytes, which interact with tumor cells." (PMID 39744475, 2025). "Responses to ICB have been associated with TIICs, an increase in tumor-infiltrating PD-1hiCD8+T cells, LAG3+CD8+T cells and monocytes/macrophages in tumor as well as S100A9+CD14+monocytes in the peripheral blood of patients exhibiting suboptimal responses to anti-PD-1 therapy." (PMID 41438767, 2025). "CD14+ tumor-infiltrating macrophages represent one of the main tumor-infiltrating immune cell types and are generally categorized into either of two functionally contrasting subtypes, namely classical activated M1 macrophages and alternatively activated M2 macrophages." (PMID 40244064, 2025). "They showed that high TGFB2 mRNA levels were associated with an immunologically “cold” tumor microenvironment (TME), characterized by low expression of antigen-presenting cell (APC) markers (e.g., CD14, CD163, ITGAX/CD11c), which impairs anti-tumor immune responses." (PMID 41373732, 2025). "When monocytes transform to dendritic cells via tumor stroma-derived factors, the expression of CD14 and PD-L1 may elevate and hinder the destruction of immune cells in PCa." (PMID 40235543, 2025). "Ang 2, a ligand of Tie 2, is primarily identified within cancer cells, and may induce transmigration of Tie2/CD14+CD16+ monocytes into the tumor tissues." (PMID 41142828, 2025). "In addition, reduced expression of CD14 + monocytes, which are typically involved in inflammatory responses within the tumour microenvironment, suggest reduction in tumour growth, decreased progression and metastasis." (PMID 40652143, 2025). "Additionally, while we have identified CD14 as a key player in the immunopathogenesis of GC, the precise molecular mechanisms by which CD14 influences tumor progression and immune evasion require further elucidation." (PMID 40092684, 2025). "The key question is whether MYXV influences or even subverts immunosuppression by CD14+ TAMs to enable a more effective anti-tumor CD4+ T cell response." (PMID 40872773, 2025). "Moreover, a significant reduction in tumor-infiltrating CD14+ monocytic cells was observed in the group treated with PTSO-modulated hPBMCs compared to the control group." (PMID 41010517, 2025).
tumor (continued). "It is known that in OC CD14+ TAMs suppress the anti-tumor function of CD4+ T cells." (PMID 40872773, 2025). "Indeed, in OS and EwS patients tumor infiltrating CD14+CD16+ myeloid cells show a TNF signaling signature." (PMID 39723214, 2024). "Similarly, CD206+ CD14+ monocyte-derived macrophages were also enriched within the tumor in our study." (PMID 39761010, 2024). "Furthermore, the CD14+ monocyte with the highest angiogenesis score played a crucial role in tumor progression (p < 2.2e−16)." (PMID 38600248, 2024). "A higher proportion of tumor cells in dogs with AML were labeled with the anti-CD80 antibody vs antibodies against other myeloid-associated antigens, including CD4 (36%, p = 0.003), CD11b (44%), CD11c (46%), CD14 (38%, p = 0.006) and CD18 (59%, clone YFC118)." (PMID 39224452, 2024). "Furthermore, SPP1+ macrophage was revealed to have an immunosuppressive function, and CD14+ monocyte was found to contribute to tumor progression and angiogenesis." (PMID 38600248, 2024). "Both CD14+APOE+ cells and MMP7+ tumour cells were associated with worse survival." (PMID 39187937, 2024). "CD14+HLA-DR expression has been reported as a predictor of immunotherapy response, with increased expression suggesting activation and greater presentation of tumour neoantigens to reactivated T cells, favouring positive therapy outcomes." (PMID 38804366, 2024). "Additionally, the KLF2 maintaining tumour cells survival, exhibited heightened regulon activities in CD14+APOE+ cells." (PMID 39187937, 2024). "CD14 + cells within tumors and distant lung tissues significantly elevate the expression of these molecules compared to peripheral blood CD14 + monocytes, indicating a high degree of heterogeneity but consistent upregulation in the tumor context." (PMID 39068459, 2024). "Tumor area was identified by tumor score and CD14 was used to label mononuclear phagocytes." (PMID 38408082, 2024). "Notably, our results suggest that CD14+ TAMs significantly enhanced tumor SFE and the proportion of CD133+ CD44+ cells in GBC cells." (PMID 39138521, 2024). "Earlier studies also reported that HLA-DR expression on tumor-infiltrating monocytes correlates with high levels of PD-L1, suggesting that the increased PD-L1+ CD14+ cells found in R patients in our cohort may have these functional characteristics." (PMID 38790920, 2024). "Moreover, CD1c+CD14+ cells show a defective stimulatory capacity of tumor antigen-specific CD8 T cell responses compared with CD1c+CD14− cells." (PMID 38242119, 2024). "We discovered that the SPP1+ macrophage was more likely to be M2-like, and the CD14+ monocyte could contribute to tumor angiogenesis." (PMID 38600248, 2024). "In addition, we observed a significantly higher level of ICAM-1, which has been suggested as an important mediator of CD14+ monocyte adhesion in tumor microenvironment." (PMID 39201392, 2024). "Notably, CD14+APOE+ cells were predominantly located in areas with high MMP7+ tumour cells, suggesting a strong co‐localisation pattern between MMP7+ tumour cells and CD14+APOE+ cells." (PMID 39187937, 2024). "The number of TAMs (CD206+) in xenograft tumours was significantly decreased in the mice sh‐circ group compared to the NC group, and the number of monocyte (CD14+) in xenograft tumours was significantly increased in the mice sh‐circ group compared to the NC group." (PMID 38506082, 2024). "This quantification revealed that areas with high MMP7+ tumour cells had more CD14+ cells." (PMID 39187937, 2024). "On the other hand, CD206-expressing monocytic cells are classically associated with an anti-inflammatory phenotype, as described for in vitro differentiated regulatory macrophages or infiltrating CD14+ CD206+ tumor monocytes, which specifically express Arginase-1, IL-10, and TGFβ." (PMID 39845960, 2024). "We demonstrate conversion of CD5+/−CD1c+CD14− cDC2s to CD14+ cDC2s by tumor-associated factors, whereas monocytes failed to express CD1c under similar conditions." (PMID 38242119, 2024).
tumor (continued). "However, we demonstrate that monocytes are incapable of transdifferentiating to CD1c+CD14+ DCs in response to tumor cues." (PMID 38242119, 2024). "Nearest-neighbor analysis revealed that both immunosuppressive and proinflammatory macrophages are nearest PanCK+ tumor cells, CD14+ myeloid cells, and other CD68+ macrophages and are farthest from CD66b+ neutrophils and CD3+ T cells in the TME of bone metastases." (PMID 38193534, 2024). "Interestingly, classical monocytes (LY6Chi/CD14+ CD16−) are also believed to be recruited to tumor microenvironment, where they play a pro-angiogenic role, thereby promoting tumor growth." (PMID 39201392, 2024). "To assess whether DCs and monocytes can give rise to tumor-induced CD1c+CD14+, we started in vitro differentiation assays with CD14− cDC2s or CD14+ monocytes isolated from HD PBMCs (purity ≥ 95%)." (PMID 38242119, 2024). "Subsequently, we examined the clinical importance of MMP7+ tumour cells and CD14+APOE+ cells." (PMID 39187937, 2024). "Additionally, a study showed that Ccl15 expression in HCC patients correlates with a poor clinical outcome, increased tumor cell invasion and recruitment of immune-suppressive CD14+ monocytes." (PMID 38673795, 2024). "Our study indicated that NCRT could reduce CD19 + B cell infiltration and CD14 + monocytes in the tumor microenvironment." (PMID 38926205, 2024). "It was also shown that a positive correlation existed between the expression level of CAXII and glucose transporter GLUT1 in tumor-purified CD14+ cells, which may affect the glycolytic switch in tumor-infiltrating monocytes and macrophages." (PMID 37006233, 2023). "The panel could detect subsets of monocytes expressing CD14 and MHC-II or CD4 and demonstrated that neutrophils in the tumor were characterized as CD14–MHCII–CD4+." (PMID 36996049, 2023). "LAIR-1 was observed to be expressed on pan CK+ tumor cells and CD14+ monocytes." (PMID 36960400, 2023). "Less common immunosuppressive cell types in human HCC consist of B cell population expressing PD-1, Th17 cells, CD4+ T cells expressing CCR4 and CCR6, CD14+ DCs expressing CTLA-4 and PD-1, tumor-associated neutrophils, tumor-associated fibroblasts, and type-II T helper cells (Th2)." (PMID 36845131, 2023). "In addition, monocyte/macrophage markers (CD14, CD68, and CD163) were also lower in the tumor core of liver metastases, but CD14 and CD163 were more abundant in peritumoral regions of liver metastases than lung or peritoneal metastases." (PMID 37768208, 2023). "Indeed, tumor-enriched FCN1+ monocyte-like cells showed a high similarity to blood CD14+ monocytes, representing a monocyte population migrating into tumors and harboring a tumor-specific transcriptional program." (PMID 38347955, 2023). "Notably, tumor-infiltrated CD14+ cDCs express high levels of markers that are characteristic of tumor-associated macrophages (TAMs), such as CD206, MerTK and CD163, suggesting that these cells exhibit TAM-like protumoral functions." (PMID 36949244, 2023). "Monocytes (CD14; p = 0.001), conventional dendritic cells (CD11c; p = 0.04), and antigen-presenting cells (CD40; p = 0.01) were all elevated in high TILs, with each being linked to either immunosuppression and/or tumor proliferation." (PMID 37627156, 2023). "This phenotype could correspond to antigen presenting cells-like hybrid tumour associated neutrophils (APC-like TAN) in which markers for both granulocytes (CD11b, CD66b, CD15) and monocytes (CD33, CD14, HLA-DR, CCR7, CD86, CD20) co-exist." (PMID 36189320, 2022). "To explore whether such a metabolic switch might play a role in the induction of CA12 expression on these cells, we purified CD14+ cells from tumor tissues of HCC patients." (PMID 35362480, 2022). "We hypothesized that increased CD14+ cells within the tumor microenvironment (TME) could stratify patient outcomes." (PMID 36139660, 2022).